FAM151B-DT (FAM151B divergent transcript)
Synonyms: SLC7A11AR
Gene: Long non-coding RNA gene on chromosome 5 (80,411,231 to 80,488,101, reverse strand). Ensembl gene ENSG00000249042.
Diseases named in the same sentence as FAM151B-DT in open-access papers:
FAM151B-DT is named in the same sentence as 5 diseases in open-access papers, as found by Europe PMC text mining. Sharing a sentence is not in itself a finding about the gene and the disease.
FAM151B-DT shares sentences with these, for which no sentence is quoted: cancer (1 paper); lung adenocarcinoma (1); lung carcinoma (1); lung squamous cell carcinoma (1); tumor (1).